ISG15 (ISG15 ubiquitin like modifier)
Diseases named in the same sentence as ISG15 in open-access papers (continued):
Sharing a sentence is not in itself a finding about the gene and the disease.
infection (continued). "In this report, we show that infection of primary cervical epithelial cells, as well as of the HeLa cell line, by C. trachomatis elicits a strong induction of the expression of the ubiquitin-like molecule ISG15, and that this molecule acts as a brake on the immune response to infection." (PMID 39345209, 2024). "Both MVA recombinants expressing the wild-type (ISG15GG) or the mutated (ISG15AA) ISG15 forms induced the secretion of IFN-I in infected macrophages at 6 and 16 hpi compared with the parental MVA-Δ3-GFP, with the highest levels detected after MVA-Δ3-ISG15AA infection." (PMID 37313341, 2023). "It has been shown that in MLE-15 cells, the infection of RSV with G gene deletion (RSVΔG) could stimulate significantly higher levels of ISG15 compared to that of the WT virus, indicating that the G protein plays a critical role in modifying the expression of ISG15." (PMID 35308390, 2022). "Based on our observation of a dose-dependent decrease in conjugated-ISG15 levels at 24 hpi and thereafter increase at later stages (48 h) of infection, it is tempting to speculate that PLpro may play a significant role in early infection, that requires further validation." (PMID 34006825, 2021). "Additionally, we observed induction of Isg15 at 8h post infection in equine BAL cells." (PMID 34473814, 2021). "Thus, although ISG15 may be necessary for autophagy-mediated infection restriction as observed with knockout-based studies, its individual ectopic expression may not be sufficient to induce this mechanism of infection restriction." (PMID 34871166, 2021). "Since Listeria can provoke ISG15 induction in an interferon-independent manner, we assessed whether there was a potential bias toward ISGylation of proteins induced by infection, which could correlate with cotranslational modification, as determined by quantitative proteomics of the input." (PMID 31772204, 2019). "Therefore, the USP18C61A/C61A ISGylome could potentially represent a distinct subset of ISG15 substrates, which could hypothetically need to be more rapidly removed during the course of an infection for proper antibacterial immunity." (PMID 31772204, 2019). "We next assessed whether ISG15 has a functional effect on infection." (PMID 26259872, 2015). "Importantly, the infection with NSDV itself did not cause a reduction in the total amount of mono-ISG15 expressed from the transfected plasmid, as shown by tracks 5-7 of fig." (PMID 22163042, 2011). "Infection of human primary epithelial and endothelial cells and mouse FGT organoids with Ct and Cm induced high protein expression and secretion of ISG15." (PMID 40627782, 2025). "The induction levels of antiviral genes—including DDX58, OAS1, OAS2, ISG15, MX2, IFI44L, RTP4, and IFNB1—were markedly reduced in KO cells compared to WT cells post-infection." (PMID 40872812, 2025). "We compared TOA regimens (full, pre, co, post), evaluated combinations with nirmatrelvir (NL63) or GS-441524 (OC43) using ZIP scores, and profiled infection-context transcripts (IL6, IFNB1, ISG15, NRF2/antioxidant, UPR)." (PMID 41304814, 2025). "We investigated the function of secreted ISG15 in the innate immune response against Ct using murine FGT organoid and murine in vivo infection models." (PMID 40627782, 2025). "ISG15 was secreted into the FGT and was involved in controlling bacterial load in a murine infection model." (PMID 40627782, 2025). "For the lung tissue explants, influenza H5N1 virus infection significantly induced the mRNA expression of ISG15, MCP-1, and MDA-5 and trends in the upregulation of IFN-α, IP-10, and IL-6 were also observed when compared with mock infections." (PMID 40431161, 2025). "Following Ct infection, ISG15−/− mice exhibited reduced IFN-γ levels at 3 and 7 dpi, consistent with ISG15 regulating the early, innate IFN-γ response mediated by NK cells." (PMID 40627782, 2025).
infection (continued). "Nonetheless, we observed decreased ΔORF2 replication over time as well as a significantly stronger induction of ISG15 compared to HEV WT on days 5 and 7 post-infection." (PMID 40982567, 2025). "Marc-145 cells were infected with PRRSV at varying multiplicities of infection (MOIs), and cell samples were collected to measure the mRNA levels of IFN-β and ISG15." (PMID 41070967, 2025). "In the brain, infection with Bov342 induced the expression of type-I (Ifna5, Ifnb), -II (Ifng), and -III (Ifnl2) interferons (IFN), interferon stimulated genes (ISGs) (Isg15, Ifit1, Mx1, Oas1), and pro-inflammatory cytokines (Il1b, Il6, and Tnfa) at endpoint." (PMID 40410375, 2025). "Similar to our findings made by EPO of HepG2/C3A cells, expression of ISG15, IFNL1, and an additional ISG, IFIT1, peaked on day 5 post-ΔORF2 infection and decreased again to a similar level as WT on day 7 post-infection." (PMID 40982567, 2025). "In addition to a possible antagonist role with ubiquitin, free ISG15 has been demonstrated to act as a negative regulator of Nedd4 in humans – this may explain the large increase of ISG15 at 48 hours post infection, paralleled with the large reduction in abundance of Nedd4 family proteins." (PMID 41181121, 2025). "Our findings illustrate that the vOTUs from YEZV and JCTV can cleave both Ub and ISG15 in an overexpression system, but these viruses exhibit potentially narrower deISGylation capacity than CCHFV during natural infection." (PMID 39745436, 2025). "The mRNA expression of IL-29, TNF-α and IFN-β for the G4 swine viruses were similar to the level achieved in G1, whereas the expressions of ISG15 and MX1 were particularly high in H1N1/pdm/09 infection." (PMID 40742730, 2025). "Since our previous data demonstrated that ISG15 can induce IL-10 release, we monitored IL-10 production in the FGT tissues of mice following Ct infection." (PMID 40627782, 2025). "We found that interferon-stimulated genes, crucial for restricting respiratory virus replication early after infection, such as CXCL10, CXCL9, CXCL11, OAS1, OASL, and ISG15, were significantly upregulated in PCLS 72 h post-infection." (PMID 41239423, 2025). "Consistently, ASFV-WT infection markedly dampened the mRNA levels of ISG54, ISG56, ISG15, and MX1, which are spurred by IFN-β in PAMs." (PMID 40618140, 2025). "In mice, we observed that ISG15 displayed a marginal role in modulating the production of IFN-γ, a key component of the host immune response to infection, but facilitated bacterial clearance." (PMID 39345209, 2024). "Nevertheless, the upregulation of CXCL10 (at the protein level) or ISG15 mRNA, both of which are induced by type I interferon, indirectly demonstrated the efficient establishment of the IFN response upon infection." (PMID 39345143, 2024). "Primary human Sertoli cells infected with either 5 or 10 MOI of the Zika virus showed a prominent, dose dependant, increase in the expression of ISGs including ISG15, OAS1, IRF1, and IFI6 48 hours post-infection, compared to uninfected controls at 8 hours." (PMID 39621805, 2024). "ISG15 expression is strongly induced by type I IFN and other stimuli, such as type II and III IFN, genotoxic stressors, pathogen infection, lipopolysaccharide, and retinoic acid." (PMID 38400136, 2024). "As shown in, we observed that knockdown or overexpression of MDA5 can significantly inhibit or promote the expression levels of IFN-1, Mx1, ISG15, and Viperin upon SCRV infection or poly(I:C)-HMW stimulation." (PMID 39347580, 2024). "In individuals affected by influenza virus infection, IFFI44L, ISG15, IFIT3, and RSAD2 are crucial antiviral factors inhibiting infection within alveolar basal epithelial cells." (PMID 38601162, 2024). "The significant involvement of Interferon-Stimulated Genes (ISGs) like ISG15, OAS1, and MX1 throughout the infection period underscores the critical role of interferon responses." (PMID 38957806, 2024).
infection (continued). "CCL2 and CXCL10 transcripts were upregulated after 30 days and 60 days of infection, as were IFN-a, IFN-b, ISG15, and IFI16 transcripts." (PMID 38737767, 2024). "The knockdown of RIG-I inhibits the IFN pathway and the ectopic expression of ISG15 and MX1 inhibits the infection of FMDV." (PMID 38512977, 2024). "ISG15 and its binding partner USP18 are crucial for IFN-I pathway down-regulation, which is pivotal for infection control and immune-regulation in humans." (PMID 38384473, 2024). "Multiplex ELISA assay on culture supernatants confirmed that infection-stimulated secretion of IL6 and IL8, as well as of several other cytokines and chemokines, was reduced in cells expressing ISG15 compared with ISG15-KO HeLa cells." (PMID 39345209, 2024). "We found that the type I interferon (IFN-I)-related genes, DDX60, IFI16, IRF7, ISG15, OAS1, and STAT1, were more highly expressed after Omicron breakthrough infection." (PMID 39835127, 2024). "Four important antiviral ISGs, MX1, MX2, ISG15, and IFI6, were found to be upregulated after infection with either strains of IAV in the lower trachea." (PMID 39247193, 2024). "In summary, these results demonstrated that infection with a virulent CSFV Shimen strain can induce the expressions of TRAF1, RIG-I, MAVS, IRF1, and ISG15." (PMID 38995016, 2024). "Infection with MR766MC induced expression of IFN-β and ISGs with antiviral effectors such as Mx, OAS, IFIT, ISG15, and viperin." (PMID 39178324, 2024). "Included in this set are critical genes like ISG15 and HERC5, indicating a potentially universal defense tactic early in infection." (PMID 39591472, 2024). "To further confirm that pK205R antagonizes IFN-I signaling through the IFNAR during ASFV infection, we monitored the transcriptional levels of ISG15, ISG54, and ISG56 induced by ASFV-WT and ASFV-pK205R7PM at different time points of infection with PAMs." (PMID 39405340, 2024). "Only five DEPs were common for both infections in both upper and lower trachea, including four interferon stimulated proteins (OASL, MX1, IFIT3, and ISG15) and the GTPase, DRG2." (PMID 39247193, 2024). "Ovine cells reacted with especially strong upregulation of Isg15, Isg20, and Ifnb-2 after BATV, lNRIV, or BAYAV infection." (PMID 39772143, 2024). "While the number of significantly upregulated genes decreases to 37, these genes (e.g., ISG15, IFI6, IFI44L, HP, OAS1, IFI44, OASL, and IFI27) likely play a crucial role in the response to the progressing infection." (PMID 39282474, 2024). "Consistently, knockdown of PCGF3 increased the expression levels of ISGs (ISG15, IFIT1, OAS2, MX1 and IRF7) and IFNB1, and decreased the VSV replicates (RNA level and virus titer) after VSV infection." (PMID 39368978, 2024). "The 17 DEGs upregulated after infection with huH1N1 were shared with the swH1N1 infection (DDX58 (RIG-I), RSAD2 (Viperin), MX2, MX1, OAS1, ANGPTL4, IRF7, ISG15, IFIT1, ISG12(A), DDX60, BST2, IFI44, XAF1, LGALS3BP, RTP4, and IFI6)." (PMID 39247193, 2024). "Along with STAT1, MX1 and ISG15 were upregulated in the present study, similar to HUVEC cells after infection by Rickettsia conorii bacterium." (PMID 37384298, 2023). "Interferon-stimulated genes such as Isg15, Isg56 (IFIT1), and Interferon-induced GTP-binding protein Mx1 (Mx1) were strongly induced following infection." (PMID 36851549, 2023). "RGNNV infection induces high levels of the ISG-12 protein in the sea bass comparable to those of Mx and ISG-15." (PMID 38068937, 2023). "Our findings demonstrate that PAstV1 infection induces a type I IFN response and that ISG15 and ISG56 mRNAs are detectable 12 h after infection with this virus." (PMID 37140381, 2023). "To rule out a delay in the infection of Isg15−/− MEFs as the cause of reduced actin tail formation and EV release, we analyzed the levels of early (E3) and late (A27 and F13) viral proteins by Western blotting in infected Isg15+/+ and Isg15−/− MEFs (2 PFU/cell) at 9 and 16 hpi." (PMID 37036376, 2023).
infection (continued). "Shared genes upregulated with a higher log2 fold change in B/Victoria infection included known anti-viral proteins IFIT1-3, IFITM1, MX2, IFI44L and ISG15 along with mitochondrial-related gene CMPK2." (PMID 37766362, 2023). "Our results demonstrate that while mRNA levels of Ceacam1 remained unchanged among groups, those mice supplemented with vitamin D exhibited elevated expression of Ifnb1, Isg15, and Isg20 following MHV-3 infection." (PMID 38140675, 2023). "The upregulation of ISG15, ISG20, ISG15 family ligases (HERC5/6), and ISG15 proteases (USP18) also appeared upon infection, which has been reported to participate in host antiviral immunity." (PMID 37752509, 2023). "Targeting of human-specific ISG15 by B-NS1 suggests an integral role between IBV replication and the human IFN response during infection." (PMID 37896807, 2023). "Our findings highlighted distinct differences between the infection groups of CT-P10 and CT-P120 PEDV strains, specifically in the expression levels of proteins such as TRAF3, IRF3, NFKB1, and ISG15." (PMID 37515115, 2023). "Many antiviral ISGs were upregulated in early stages of infection, with IFI27, OTOF, ISG15, MX1 and USP18 the most highly overexpressed." (PMID 37077524, 2023). "The higher expression of FTH1, ISG15, SRGN and S100A12 genes observed in infected animals suggests the activation of the host immune system to resist the infection." (PMID 37761803, 2023). "We observed that vesicular stomatitis virus (VSV, a type of RNA virus) infection and IFN-β stimulation induced HERC6 and ISG15 expression in mouse PMs." (PMID 37651190, 2023). "Knockdown of circMORC3 can significantly promote the expression levels of ISG15, Mx1 and Viperin upon SCRV infection." (PMID 38150467, 2023). "Deletion of ORF8 increased the early expression of MX1 and ISG15 at 1 dpi in the lungs of mice and IFNβ in human organoids at 24 hpi, suggesting that ORF8 is an IFN antagonist at early times post-infection." (PMID 37623322, 2023). "The expression levels of IFN-β, IL-29, ISG15, and MxA were diminished in PD-L1-overexpressed cells during WSN or PR8 infection, determining that PD-L1 mediates immunosuppression by negatively regulating the expression of the cytokines induced by IAV infection." (PMID 37239931, 2023). "After NSV2 treatment, a large amount of free ISG15 was accumulated in the early stage of PRV infection, while a large number of ISG15 conjugates appeared in the early stage of infection." (PMID 37256060, 2023). "As expected, the similar diminished expression levels of IFN-β, IL-29, ISG15, and MxA were also observed in PD-L1-overexpressed cells upon PR8 infection." (PMID 37239931, 2023). "EECs were transfected with ISG15 siRNA or control siRNA, and, after 24 h, they were infected with PPRV (multiplicity of infection [MOI] of 1)." (PMID 36036587, 2022). "Indeed, several key antiviral effectors and inflammatory drivers remained upregulated at late infection time points in older mice when compared to the 10 w-old animals, including several that were poorly upregulated initially in the older cohort; these included Il6, Isg15, Cxcl10, and Ifit2." (PMID 36679892, 2022). "This was the case for the type I IFN response, but also for RIPK1, STAT1, DDX58, ISG15, TRIM25, and MYD88, involved in TNF-, TLR-, RLR-, and NFκB signaling, 48 h after MOPV infection." (PMID 35337059, 2022). "We infected IFN-treated Isg15−/− and WT BMDMs with VACV WR (multiplicity of infection [MOI] of 1 for 16 h) and analyzed the LD content by confocal microscopy." (PMID 36453897, 2022). "Prior to infection with PRV, PK15 cells were transfected with either a control siRNA or a siRNA targeting UbE1L, and expression of free ISG15 and conjugates were measured by immunoblotting." (PMID 36315588, 2022). "In our study, overall, exposure to NPs reduced the up-regulation provoked by the NNV infection regarding the main IFN genes, namely, mx and isg15." (PMID 35163406, 2022).
infection (continued). "The results showed TRIM18 KO BMDM produced significantly more IFN-α and IFN-β proteins and mRNAs of ISG15 and ISG56 than WT BMDM after infection with DNA viruses." (PMID 35909127, 2022). "As seen in the DLB-1 cell line, RGNNV infection of L. japonicus brain cells (LJB) resulted in immune response regulation and apoptotic-related proteins’ transcription (e.g., ISG15, IRFs, TLRs, HSPs) to assist the virus in escaping the host antiviral response." (PMID 35215144, 2022). "Results showed that MX1, MX2 and OAS1 were over-expressed in SARS-CoV-2-infected A549 cells (p < 0.01 for MX1, ISG15, and OAS1; and p < 0.05 for MX2), and Calu-3 cells (p < 0.05 for MX1, ISG15, and OAS1; and p < 0.01 for MX2) compared with mock infection." (PMID 36298734, 2022). "Compared with WT BMDM, TRIM18 KO BMDM produced 2- to threefold more IFN-α and IFN-β proteins and twofold more mRNAs of ISG15 and ISG56 post-infection by RNA viruses Flu PR8 and CVB3." (PMID 35909127, 2022). "Induction of the IFN I pathway after infection with the wt isolate was evident by up-regulation of several interferon-induced proteins, i.e., IFIT-I, ISG15, IFI44, GIG1, interferon-induced very large GTPase 1, IRF3, IRF7, and Mx." (PMID 35215144, 2022). "We sought to dissect the expression of free ISG15 and ISG15 conjugates during PRV infection with different multiplicity of infections (MOIs) and different times post-infection." (PMID 36315588, 2022). "EECs were transfected with Myc-ISG15, ISG15AA, and Myc empty as control, followed by PPRV infection." (PMID 36036587, 2022). "Four strains with the highest viral copy numbers (n = 4) and three strains with the lowest viral copy numbers (n = 3) were selected to evaluate TNF-α, IL-6, IFN-β, ISG-15, IFITM1, and TRIM22 expression levels at 6 h post-infection." (PMID 36146585, 2022). "In parallel with the induction of STAT1 expression, transcription of some IFN stimulated genes (ISGs) was also noticed upon USUV infection of JAR cells, such as OAS2 and ISG15." (PMID 35893684, 2022). "Considering the role of ISG15 as a regulator of macrophage metabolism during VACV infection, in this study, we explored how ISG15 controls macrophage lipid metabolism and how its presence or absence affects how VACV modulates lipid metabolism during infection." (PMID 36453897, 2022). "Further, SARS-CoV-2 infection significantly induced these ISGs in ferret tracheal biopsy samples collected on day 3 after infection compared with mock-treated animals (p < 0.01 for MX1; and p < 0.05 for MX2, ISG15, and OAS1)." (PMID 36298734, 2022). "Of note, we observed that several duck IFN-stimulated genes (ISGs), including IFI35, Mx, ISG15, ZC3HAV1, LGP2, IFITM1, IFITM2, and Viperin, were dramatically upregulated upon DTMUV infection." (PMID 34335626, 2021). "We showed that cytosolic nucleic acid signaling pathway-related proteins such as IFIH1 (MDA5), ISG15, IFI202 and IFI204 were significantly upregulated in the M28ΔtatA/M28 infection group." (PMID 34195100, 2021). "The results of the present study demonstrated that ISG15 inhibited the TLR4/NF-κB signaling pathway, and such temporary immune tolerance may lead to weakened identification of pathogenic microorganisms in the body during this period, thus increasing the risk of infection." (PMID 34573559, 2021). "Analysis of the IFN-stimulated genes (ISGs) Ifitm3, Irf7, Isg15, and Oas1a at 12, 24, and 72 hpi demonstrated a consistent trend for increased expression following ZIKVCDN infection." (PMID 34193875, 2021). "In the presence of HO infection, the stimulatory effect of IFNT on expression of GBP4, ISG15, HERC5, RSAD2, IFIH1, IFIT3, and MX1 was significantly reduced (IFNT vs. IFNT+HO, P < 0.05–0.01)." (PMID 33898551, 2021). "Infection of HeLa cells and primary MRC-5 fibroblasts with SeV led to the TFG-dependent production of detectable amounts of ISG15, ISG54 and ISG56 proteins." (PMID 33411856, 2021).